NEDD9 (neural precursor cell expressed, developmentally down-regulated 9)
Diseases named in the same sentence as NEDD9 in open-access papers (continued):
Sharing a sentence is not in itself a finding about the gene and the disease.
breast cancer (continued). "In the past several years, NEDD9 has been studied in breast cancer, as a cancer cell-intrinsic protein with a pro-oncogenic role and as a candidate biomarker of tumor aggressiveness." (PMID 22869051, 2012). "Similar results were obtained with HCC1937 human breast cancer cells when NEDD9 expression was repressed by siRNA (Figure." (PMID 21829474, 2011). "To summarize, we validated in this study that the expression of NEDD9 was frequently upregulated in highly aggressive TNBC breast cancer cell lines as well as in aggressive breast tumors, including ERBB2-positive and triple-negative subtypes." (PMID 21829474, 2011). "We then employed immunohistochemistry (IHC) to assess the NEDD9 protein expression in the paraffin-embedded mammary tissue sections from 84 breast cancer patients in parallel with the surrounding normal breast epithelia." (PMID 21829474, 2011). "In this study, we wished to discern the role of NEDD9 in breast cancer progression and to investigate the molecular mechanism by which NEDD9 regulates EMT and promotes invasion in triple-negative breast cancer." (PMID 21829474, 2011). "Recent studies showed that Nedd9-null genetic background significantly limited mammary tumor initiation in the MMTV-polyoma virus middle T genetic model, suggesting that NEDD9 expression played an important role in breast cancer." (PMID 21829474, 2011). "To validate this, we examined the function of NEDD9 in breast cancer by repressing its expression in two highly aggressive TNBC cell lines, MDA-MB-231 and HCC1937." (PMID 21829474, 2011). "Collectively, these data suggest that NEDD9 is dominantly overexpressed in human aggressive breast cancer." (PMID 21829474, 2011). "NEDD9 was identified as one of a few critical genes that mediate metastasis in melanoma and breast cancer." (PMID 20825672, 2010). "Notably, FAK inhibitors reversed breast cancer metastasis induced by NEDD9 upregulation via pan-HDAC inhibitors." (PMID 39199304, 2024). "Furthermore, SOX2 promotes the migration of breast cancer cells by inducing the expression of neural precursor cell expressed developmentally down-regulated protein 9 (NEDD9)." (PMID 37511298, 2023). "In this study, we determined that pan-HDAC inhibitors elevate NEDD9 expression and promote breast cancer metastasis, which might be one of the reasons of its clinical failure." (PMID 36604412, 2023). "While deletion of NEDD9 is not observed in human breast cancers, the upregulation of NEDD9 has been linked to tumor progression and metastasis in various cancers, including breast, liver, colon, pancreatic, ovarian, lung, and brain." (PMID 36831460, 2023). "NEDD9 levels were determined in a small panel of human breast cancer cell lines." (PMID 36604412, 2023). "Our results suggest that NEDD9 is essential for the promotion of breast cancer metastasis." (PMID 36604412, 2023). "Similarly to TMA findings, NEDD9 protein was increased in a panel of HER2+ breast cancer cell lines (BT-474, SK-BR-3, JIMT1, and JIMT1-Br3) when compared to non-transformed MCF10A cells." (PMID 36831460, 2023). "The overexpression of NEDD9 in HER2+ breast cancer correlates with reduced relapse-free survival." (PMID 36831460, 2023). "In this study, we declare that pan-HDAC inhibitors targeting NEDD9-FAK pathway exacerbate breast cancer metastasis in preclinical models, which may severely impede their clinical success." (PMID 36604412, 2023). "These subcutaneous tumour models indicated that miR-107 may participate in the development of breast cancer by regulating NEDD9 in vivo." (PMID 35549691, 2022). "ZMYND10 suppresses breast cancer oncogenicity by inhibiting the miR145-5p/NEDD9 signaling pathway." (PMID 36158689, 2022). "As a metastasis-related protein, NEDD9 has been reported in breast cancer (BC) metastasis research." (PMID 35549691, 2022).
breast cancer (continued). "Moreover, overexpression of NEDD9 correlated with cancer cell development and drug resistance in several types of solid tumours such as lung cancer, melanoma and breast cancer." (PMID 34432355, 2021). "The qPCR assay data showed that miR-145-5p inhibitor was added to ZMYND10-expressing breast cancer cells could reduce the expression of miR145-5p and increased the expression of NEDD9." (PMID 31801619, 2019). "Our study is the first to reveal that SOX2 and NEDD9 may function as novel upstream regulators of Rac1/HIF-1α in hypoxic breast cancer cells." (PMID 31462898, 2019). "It is therefore interesting to investigate whether Rac1 and HIF-1α work as downstream effectors of SOX2 and NEDD9 in hypoxic breast cancer cells." (PMID 31462898, 2019). "However, what is different from the mammary tumor cells is that NEDD9 knockdown in pancreatic cancer cells mainly decrease phosphorlyation of Akt at T-308, but not at S-473." (PMID 28915595, 2017). "Furthermore, the establishment of aggressive breast cancer phenotype following upregulation of NEDD9 is accompanied by increased expression of serglycin, its cell surface binding partner CD44, and CS synthesizing enzymes." (PMID 26581653, 2015). "Given the increasing evidence that depletion of Nedd9 drastically reduces migration and invasion of highly metastatic mammary tumour cells, inhibition of Nedd9 expression and/or activity represents an attractive strategy to target aggressive breast cancer cells." (PMID 25606587, 2014). "In addition to its role in regulating the mitotic cell machinery, Nedd9 cooperates with AurA to control actin cytoskeleton dynamics and motility of breast cancer cells." (PMID 25606587, 2014). "In MCF7 cells, oestrogen treatment stabilizes the 105 kDa Nedd9 form and suppresses the ability of Nedd9 to induce cell spreading, thus suggesting that Nedd9 phosphorylation status might be an indicator of breast cancer cell motility in response to oestrogens." (PMID 25606587, 2014). "The integrin adaptor NEDD9 impairs migration and invasion in breast cancer and cervical cancer." (PMID 25504435, 2014). "Beyond its function as a mediator of a variety of integrin-dependent processes, such as cell adhesion, survival and migration, Nedd9 can further impact on mammary tumour cell behaviour through its ability to directly activate the mitotic regulatory kinase Aurora-A (AurA)." (PMID 25606587, 2014). "Thus, it is possible that CSPG4 expressed on breast cancer cells would transduce signals by forming a complex with NEDD9 for promoting migration, invasion, and growth in surrounding tissues." (PMID 22984505, 2012). "Thus, our results support the notion that NEDD9 promotes migration and invasion of TN breast cancer cells and would be a promising target for therapy of TN breast cancer." (PMID 22984505, 2012). "Indeed, TGF-β, retinoic acid, and progesterone receptor A have all been reported to up-regulate the NEDD9 transcription, whiles estrogen down-regulated NEDD9 mRNA in osteosarcoma and breast cancer cells." (PMID 21283797, 2011). "Thus, depletion of the NEDD9 protein might provide significant benefits in treating therapy resistant HER2+ breast cancers." (PMID 36831460, 2023). "Moreover, we attempted to determine whether the high level of NEDD9 correlated with the high mobility in human breast cancer cells." (PMID 36604412, 2023). "Our findings suggest that NEDD9 plays a crucial role in HER2+ breast cancer initiation, progression, and drug response; thus, targeting NEDD9 might provide new treatment strategies for BC patients and expose new vulnerabilities that could improve patient survival." (PMID 36831460, 2023). "Therefore, it may be reasonable to speculate that the effect of NEDD9 on breast cancer cell migration is mediated by Rac1." (PMID 31462898, 2019). "Moreover, silencing of NEDD9 ameliorated hypoxia-stimulated breast cancer cell migration." (PMID 31462898, 2019).
breast cancer (continued). "Thus, overexpression of NEDD9 correlated with cell migration, invasion, metastasis development and drug resistance in several types of solid tumors such as glioblastoma, melanoma or breast cancer." (PMID 29100287, 2017). "In human breast cancer AurA expression is considered an independent marker of poor prognosis and it has been recently found that not only does it positively correlate with the expression of Nedd9 but also that co-expression of these two proteins has a significantly higher prognostic value." (PMID 25606587, 2014). "However, reports that Src and FAK activity are reduced in mouse mammary tumours derived from a NEDD9−/− mouse suggest that NEDD9 regulation of these kinases is complex and may depend on cell-type and tumorigenic status." (PMID 22509381, 2012). "Moreover, western blotting analysis of immunoreactive NEDD9 in established mammary epithelial cell lines indicated that the levels of NEDD9 in aggressive breast cancer cell lines were considerably higher than those in MCF10A cells derived from normal mammary epithelial cells." (PMID 21829474, 2011). "This suggests that NEDD9 may also play a role in breast cancer migration and invasion." (PMID 21829474, 2011). "Their data demonstrated that pan-HDAC inhibitors enhanced H3K9 acetylation at the NEDD9 gene promoter by inhibiting the HDAC4-stimulated NEDD9-FAK signaling pathway, leading to breast cancer cell metastasis." (PMID 39199304, 2024). "Marie-Line Garron and her team provide groundbreaking structural insights into the BCAR3 and HEF1 (NEDD9/Cas-L) complex, revealing its significant role in anti-estrogen resistance and integrin signaling in breast cancer." (PMID 38730626, 2024). "The results revealed a notable downregulation of AVPR1A, FEZ1, HGF, GSN, NEDD9, and EGR3 expression in the breast cancer cell lines (MCF7, BT-474, SK-BR-3, MDA-MB-231) when compared to the normal mammary epithelial cell line (MCF-10A)." (PMID 38756447, 2024). "In conclusion, we demonstrated that inhibition of HDAC4 stimulated NEDD9-FAK signaling pathway, leading to metastasis of breast cancer cell, and consequently limiting the clinical efficacy of pan-HDAC inhibitors against breast cancer." (PMID 36604412, 2023). "The results show a strong correlation between NEDD9 mRNA and relapse-free survival (RFS) in HER2+ breast cancers (BCs)." (PMID 36831460, 2023). "Homozygous MMTV-Cre-NEDD9+/+ mice and appropriate controls (MMTV-Cre and NEDD9fx/fx) were used to analyze mammary gland development and were crossed with mammary tumor models." (PMID 36831460, 2023). "However, the impact of NEDD9 expression on HER2+ breast cancers (BCs) is currently unknown." (PMID 36831460, 2023). "Overall, this data suggests that NEDD9 is elevated at the protein and RNA levels in HER2+ breast cancers, and that increased levels of NEDD9 correlate with lower RFS in the HER2+ subset of BC patients, but not in ER+ BCs." (PMID 36831460, 2023). "In such context, it is interesting to note that NEDD9 was highlighted as a positive regulator of EMT and promotes invasion in aggressive breast cancer cells such as MB-231 cells." (PMID 35158871, 2022). "In breast cancer, ZMYND10 via increasing expression of miR-145 and downregulation of NEDD9 suppressed proliferation, migration, and invasion of cells." (PMID 34479583, 2021). "We also transfected breast cancer cells with specific siRNA for SOX2, NEDD9 or the Rac1 inactive mutant (T17 N) to investigate the role of SOX2, NEDD9 and Rac1 in the response to hypoxia." (PMID 31462898, 2019). "Because ZMYND10 was reported to inhibit PI3K/AKT and NEDD9 participated in AKTactivation in certain circumstances, we examined if ZMYND10 affects this pathway in breast cancer." (PMID 31801619, 2019). "In a rescue experiment, overexpression of NEDD9 partially attenuated the ability of ZMYND10 in inhibiting migration and invasion of breast cancer cells." (PMID 31801619, 2019).
breast cancer (continued). "We have reported a longer latency until appearance of mammary tumors in MMTV-PyVT mice, and depressed activation of SRC, in the context of a Nedd9−/− versus a Nedd9+/+ genotype." (PMID 21765937, 2011). "We used breast carcinoma MCF7 cells to overexpress or siRNA-deplete BCAR1 and NEDD9, individually or in combination, and monitored total expression of E-cadherin and its partner proteins α-, β-, and p120catenin." (PMID 21765937, 2011). "Likewise, AXL-mediated NEDD9 phosphorylation is reported to recruit CrkII and thereby PEAK1, leading to altered FA dynamics in breast cancer cells." (PMID 37336884, 2023). "To date, several signalling pathways relevant to breast cancer aetiology, including transforming growth factor (TGF)-beta, progesterone and hypoxia signalling, have been found to positively regulate Nedd9 mRNA expression, but less is known about the transcriptional control of p130Cas/BCAR1." (PMID 25606587, 2014). "Nedd9 induction is necessary to establish a positive feedback loop that integrates TGF-beta/Smad and Rho-actin-SRF signalling and drives the expansion of tumour-initiating cells, selectively in claudin low breast cancer, upon TGF-beta stimulation." (PMID 25606587, 2014). "UBE2C expression was associated with that of the selected metastasis-related genes VEGF, CXCL-4, CCL5, NEDD9 and RHoC, in MCF-7 cells, so UBE2C may be involved in breast cancer metastasis." (PMID 24699941, 2014). "The results indicated that, while normal mammary epithelial cells displayed none or weak NEDD9 staining, breast carcinoma cells were positive for NEDD9 staining in cytoplasm and/or in nucleus." (PMID 21829474, 2011). "Notably, we demonstrate that FAK inhibitors can reverse breast cancer metastasis induced by upregulation of NEDD9 via pan-HDAC inhibitors, which may offer a potential combination therapy for breast cancer." (PMID 36604412, 2023). "In addition, although NEDD9 has been reported to have a hand in breast cancer metastasis, it has not received much attention, and no therapeutic strategies have been developed." (PMID 36604412, 2023). "Binding of NEDD9 to AURKA, which appears to involve NEDD9 serine (Ser) 296 and the N-terminal domain of AURKA, suppresses proteasomal degradation of AURKA promoted by the ubiquitin ligase anaphase-promoting complex/C (APC/C) in MDA-MB-231 cells, a human breast cancer cell line." (PMID 34944109, 2021). "Indeed, ER-positive breast cancer cells preferentially express a hypophosphorylated form of Nedd9 (105 kDa Nedd9) rather than the highly phosphorylated form (115 kDa Nedd9), which is known to mediate cell spreading and migration." (PMID 25606587, 2014). "However, the impact of the upregulation of NEDD9 on HER2+ breast cancers has not been explored." (PMID 36831460, 2023). "The NEDD9 expression does not influence RFS (AUC = 0.51, p = 0.35) or pCR response to endocrine therapy in ER+ breast cancers (AUC = 0.505, p = 0.47)." (PMID 36831460, 2023). "Contrary to this speculation, it was consistently observed that NEDD9 protein levels were decreased by siRNA-mediated Smurf2 depletion in HeLa cervical carcinoma cells and CN34 mammary carcinoma cells, and U2OS osteosarcoma cells (data not shown)." (PMID 20825672, 2010).
melanoma (40 papers, 2009 to 2025). A malignant, usually aggressive tumor composed of atypical, neoplastic melanocytes. "A functional study shows that NEDD9 is a potential melanoma gene for invasion and metastasis, while another study illustrates NEDD9 outcomes regarding genetic loss in a consistent phenotype." (PMID 36551688, 2022). "The increased expression of NEDD9 has been associated with the aggressiveness of lung, breast, prostate cancer and melanoma, as well as CNS, and gynecological cancers." (PMID 33485292, 2021). "Moreover, NEDD9 is a tumour-causing factor and an aggressive biomarker that influences poor prognosis and treatment resistance in melanoma." (PMID 36551688, 2022). "Additionally, NEDD9 expression negatively associated with miR‐125a/b was shown in pancreatic cancer, lung adenocarcinoma and melanoma." (PMID 34432355, 2021). "NEDD9 overexpression, as an oncogenic signaling abnormality, is associated with metastasis in several carcinomas, including glioblastomas, osteosarcomas and melanomas." (PMID 27974675, 2017). "NEDD9 has been identified as a biomarker of aggressive human tumors, including melanoma, breast, and lung cancers." (PMID 40362444, 2025). "Immunofluorescence, TCGA database and qPCR were used to analyze the correlation between the expression patterns and levels of SOX9, SOX10 and NEDD9 in melanoma patient samples." (PMID 30642390, 2019). "Lastly, SOX10 or high SOX9 expression mediates melanoma cell migration through the NEDD9-regulated focal adhesion dynamics and Rho GTPase signaling." (PMID 30642390, 2019). "This explains why low levels of SOX9 expression are negatively correlated with NEDD9 in most primary melanoma specimens." (PMID 30642390, 2019). "Accordingly, SOX10 was required for NEDD9 expression, which partly mediated its oncogenic functions in melanoma cells." (PMID 30642390, 2019). "SOX10 or high SOX9 expression regulates melanoma mesenchymal migration through the NEDD9-mediated focal adhesion dynamics and Rho GTPase signaling." (PMID 30642390, 2019). "In contrast, further elevation of SOX9 dosage corresponding to high SOX9 in metastatic melanoma specimens lead to opposite effects on p21 and NEDD9 expression with enhanced tumor growth and metastasis as well as induction of MMPs expression." (PMID 30642390, 2019). "In melanoma cells, elevated NEDD9 signaling leads to cell elongation, increased mesenchymal and decreased amoeboid cell migration." (PMID 29876004, 2018). "The consequences of these mutations on the ICAT/β-catenin complex and the transcriptional regulation of M-MITF and NEDD9 promoters were studied in two melanoma cell lines expressing opposite amounts of ICAT and β-catenin." (PMID 28273108, 2017). "In melanoma cells, mesenchymal migration was driven by activation of RAC via a complex of a Rac guanine nucleotide exchange factor DOCK3 and the adaptor protein NEDD9 (melanoma metastasis gene)." (PMID 28499439, 2017). "Investigating how ICAT is able to modulate M-MITF and NEDD9 expression in melanoma cells should help clarifying the mechanisms of interaction between ICAT and β-catenin." (PMID 28273108, 2017). "We also found the bona fide driver of melanoma metastasis and invasion NEDD9 as well as DEPDC1 and CDCA3, genes involved in progression of bladder cancer or enhanced proliferation." (PMID 24799129, 2014). "Recent reports have suggested that NEDD9 is overexpressed in some human carcinoma such as melanoma and HNSCC." (PMID 24058594, 2013). "NEDD9 has been proposed as a biomarker of invasiveness in lung cancer and melanoma due to its role in the regulation and activation of transcriptional pathways relevant for metastasis and cancer progression, including FAK and Src." (PMID 22869051, 2012). "Our data are compatible with the pro-oncogenic role identified for NEDD9 overexpression in glioblastoma, melanoma, and lung cancers." (PMID 21829474, 2011).